IL2 (interleukin 2)
Diseases named in the same sentence as IL2 in open-access papers (continued):
Sharing a sentence is not in itself a finding about the gene and the disease.
lung carcinoma (continued). "In lung cancer, TG4010, a modified vaccine targeting MUC1 and interleukin 2, showed improvements in progression‐free survival compared to placebo in a phase 2b/3 trial." (PMID 35102706, 2022). "Reishi increases significantly IFN-γ, IL-2, IL-6, and NK cells (CD56 + cells) levels in lung cancer patients thereby increasing potentially immune therapies." (PMID 35784762, 2022). "This is consistent with preceding observations from our own and other groups that markedly increased levels of cytokines, including IL-2, TNFα and CXCR4, are detected in experimental and human lung cancer tissue." (PMID 36241617, 2022). "In our previous study, a new method was developed to prime and propagate CIK cells by the combination of IL-2 and IL-15, and this kind of CIK cells had enhanced antitumor effect on lung cancer." (PMID 34540187, 2021). "In addition, IL-2 could increase the expression of PD-1 on NK cells in vitro, indicating that high IL-2 level in the plasma is largely responsible for the abundance of PD-1+ NK cells in patients with lung cancer." (PMID 32788875, 2020). "We demonstrated that the levels of IL-2, TNF-α, and IL-10 in the plasma from lung cancer patients were significantly higher than those in the plasma from healthy donors." (PMID 32788875, 2020). "Previous studies of JFK demonstrated that JFK induced lung cancer cell death by regulating some apoptotic gene expression, such as AIFM2, IL-2, and Bcl2." (PMID 29234412, 2017). "Human CD8+ TIL prepared from lung cancer patients and activated (anti-CD3/IL-2) in the presence of TWS119 for five days displayed a distinct population of CD45RAint/CD62L+ cells." (PMID 22859966, 2012). "In lung cancer patients ANOVA showed a time effect for cortisol, melatonin, TSH, CD4, CD16, CD25, TcRδ1 and IL2." (PMID 20565977, 2010). "In this study we evaluated differences among healthy subjects and subjects suffering from lung cancer in the 24-hour secretory profile of melatonin, cortisol, TRH, TSH, FT4, GH, IGF-1 and IL-2 and circadian variations of lymphocyte subpopulations." (PMID 20565977, 2010). "As a control for cytotoxic tests, we cultured regional lymph nodes from another patient with lung cancer (48-year-old man, T4N2M0, stage IIIB adenocarcinoma) in IL2 for 1 month." (PMID 19055844, 2008). "For lung cancer, a novel study demonstrated that EVs derived from human primary CD8+ T cells, containing interleukin-2 and cetuximab, exhibited enhanced antitumor activity and targeting specificity against lung cancer cells, presenting a promising therapeutic strategy." (PMID 40317075, 2025). "Exosomes from human lung cancer (H1299 and A549) cells were co-cultured in a unidirectional flow bioreactor with CD8+ T-cells immobilized onto 3D-printed RGD-functionalized poly(L-lactic) acid (PLLA) scaffolds and assessed for IL-2 production." (PMID 35323230, 2022). "A follow-up study demonstrated the cytotoxicity enhancement of TKD (antigenic component of HP70)/IL-2-activated NK cells by PD-1 blocker stimulation, which resulted in local tumor control in immunodeficient and/or immunocompetent mice, in GBM and lung cancer models." (PMID 32218162, 2020). "Here, we identified the activity of the ‘IL2 signaling events mediated by STAT5’ pathway as a robust biomarker for the response to two highly similar Bcl-2 protein–family inhibitors (ABT-263 and ABT-737) in lung cancer cell lines." (PMID 32620799, 2020). "Our results showed that acupoint stimulation has immunomodulatory effect for lung cancer patients, which was demonstrated by a significant increase of IL-2, CD3+ and CD4+ T cells, NK cells, but not CD8+ T cells." (PMID 24344728, 2013). "Our study showed that acupoint stimulation has strong immunomodulatory effect for lung cancer patients as demonstrated by the significant increase of IL-2, T cell subtypes (CD3+ and CD4+, but not CD8+ cells), and natural killer cells." (PMID 24344728, 2013).
lung carcinoma (continued). "IL-5 production was observed in MNCs from lung cancer patients stimulated with IL-2, but not with IL-15." (PMID 9744501, 1998). "Therefore, the purpose of treating lung cancer stem-like cells (hA549) with the supernatants of IL-2 and anti-CD16 antibody NK cells in the current study was to determine if IL-2 and anti-CD16 antibody-treated NK cells can mediate the differentiation of lung cancer stem-like cells as well." (PMID 39851518, 2025). "There is a lack of RCTs investigating retinoids for lung cancer treatment; a single trial exists showing clinical benefit when 13 CRA, a naturally occurring retinoid, was combined IL-2, and this on surrogate immune parameters and levels of VEGF only." (PMID 21738614, 2011). "Similarly, tumor cells from patients with advanced lung cancer express some type 2 cytokines such as IL-10 and transforming growth factor-β (TGF-β), while little or no levels of type 1 cytokines such as IL-2 and IFN-gamma were noted." (PMID 24872958, 2014).
lymphoma (104 papers, 1998 to 2026). A malignant (clonal) proliferation of B- lymphocytes or T- lymphocytes which involves the lymph nodes, bone marrow and/or extranodal sites. "Given that the patient had demonstrated the development of a clinically aggressive FL with early relapse that occurred prior to the onset of the PML, we believe that the recurrence of his lymphoma was unlikely associated with prolonged IL-2 therapy." (PMID 37822572, 2023). "In our study, rs1801131 in MTHFR was associated with time to progression and lymphoma-specific death, and rs2069762 in the promoter of IL2 with lymphoma-specific death." (PMID 25294155, 2014). "Antibody targeting of IL2 to the lymphoma-associated subendothelial extracellular matrix of the neo-vasculature accumulated IL2 in the lymphoma lesions after systemic application resulting in improved anti-tumor activity compared with un-conjugated IL2." (PMID 23028547, 2012). "In lymphoma, sIL-2Rα may present IL-2 in vitro to CD4 + T cells and cause the differentiation of these cells into FoxP3 + Treg cells, resulting in the suppression of CD8 + T cells." (PMID 32660627, 2020). "Notably, low-dose IL-2 was successfully used for the treatment or prevention of lymphomas associated with human immunodeficiency virus (HIV) infection, which include a significant proportion of EBV+ cases." (PMID 22319542, 2012). "Characterization of the IL-2-expressing cells within ALCL tumor sites is critical as these cells serve as an in vivo tissue source for IL-2 and may play a pathogenic role in lymphoma development." (PMID 23675235, 2011). "Moreover, the outcome of IL-2 treatment for NK cell-mediated killing of lymphoreticular tumors, including lymphomas that is a major cause of death in WAS patients, remains unknown." (PMID 27477778, 2016). "A phase I study assessed the safety of large multivalent immunogens (LMIs) formulated using autologous lymphoma cell membranes combined with IL-2 and granulocyte-macrophage colony-stimulating factor (GM-CSF) in dogs with untreated B-cell lymphoma." (PMID 39943162, 2025). "One study expanded T cells extracted ex vivo from dogs with lymphoma on artificial antigen-presenting cells in the presence of human interleukin (IL)-2 and IL-21." (PMID 39943162, 2025). "This approach enhanced CD8+ T-cell expansion and significantly improved survival in lymphoma-bearing mice, outperforming treatments with either IL-2 or splenocytes alone." (PMID 40143046, 2025). "We thus investigated the therapeutic efficacy of IL-2 combined with sPD1 in an A20 lymphoma tumor model." (PMID 41041051, 2025). "Using the lymphoma knowledge graph as an example, we uncovered a pathogenic mutation in JAK3, which is associated with the IL-2 signaling pathway and affects adenosine triphosphate metabolism." (PMID 41334179, 2025). "After fusion of these reactive T cells to the BW5147 lymphoma, the obtained T cell hybridoma clones were scored for their IL-2 production upon stimulation with a Spike peptide pool (INITRFQTL, IWLGFIAGL, GNYNYLYRL, VVFLHVTYV, FQFCNDPFL)." (PMID 39854619, 2024). "Previous CD19 CAR T cell studies in lymphoma demonstrated a significant association between CRS/ICANS and elevated levels of cytokines, including IFNγ, IL-2, IL-6, IL-8, IL-10, IL-15, and TNFα1,20–22." (PMID 39011120, 2024). "Our findings revealed that TFAB002s effectively lysed lymphoma B cells while demonstrating moderate increases in key cytokines such as IL-2, TNF-α, and IFN-γ." (PMID 39321199, 2024). "Expanding on the analysis of performance against lymphoma cell lines, we studied the secretion of IL-2 and IL-6 by CAR/CCR and CAR T cells." (PMID 38340727, 2024). "NK-92 cell line is an immortalized IL-2-dependent human NK cell line, originated from a patient with lymphoma, that lacks ADCC activity and KIRs but can kill cancer cells through perforin and granzyme B-mediated cytolytic activity." (PMID 38077389, 2023).
lymphoma (continued). "One example is represented by NK cells from patients with lymphoma and breast cancer that were first isolated from the blood, then stimulated overnight ex vivo with IL-2 and then re-infused in the same patient." (PMID 38077389, 2023). "The soluble interleukin-2 (IL-2) receptor (sIL-2R) has been found in supernatants of adult T-cell leukemia/lymphoma cell lines and recognized as a tumor-related biomarker of malignant lymphomas." (PMID 36357882, 2022). "The IL-2-based immunocytokines that showed positive results in preclinical lymphoma studies include L19-IL2 in NHL, HI-Leu 16-IL2 in lymphoma and HRS3scFv-IL12-Fc-IL12 in Hodgkin lymphoma." (PMID 35529882, 2022). "Most clinical trials are comparing IL-2 and IL-7/IL-15 activity in lymphoma patients (NCT02652910, NCT04186520, NCT03929107, NCT02992834), revealing the demand for testing combinatory approaches of CAR T-cells and proinflammatory cytokines." (PMID 34445701, 2021). "NK cell lines such as lymphoma-derived NK-92 are widely studied sources because of good proliferation rates and easy in vitro expansion procedures with the addition of recombinant IL-2." (PMID 34572387, 2021). "TGF-β induces the expression of Smad7 in the murine interleukin-2 (IL-2)-dependent T-lymphoma cell line CTLL2, which has high expression of the transcription factor ZEB1 and low or no expression of Smad7." (PMID 32888405, 2020). "Prompted by the observation that 3′,5′-cGMP inhibits αCD3 antibody-stimulated IL-2 production of HuT-78 T-lymphoma cells, we have performed a detailed investigation of the effects of guanosine-related compounds on HuT-78 cell apoptosis and proliferation." (PMID 32313990, 2020). "A clinical study has shown that a liposomal vaccine combined with idiotype, a tumor-specific antigen, and adjuvant interleukin-2 (IL-2) induces sustained tumor-specific T-cell responses in lymphoma patients." (PMID 32792853, 2020). "The effect of 100 μM of the purine cNMPs 3′,5′-cAMP, 3′,5′-cGMP, and 3′,5′-cIMP as well as of the pyrimidine cNMPs 3′,5′-cUMP and 3′,5′-cCMP on αCD3-antibody-induced IL-2 production of HuT-78 lymphoma cells was analyzed by ELISA." (PMID 32313990, 2020). "Single cell suspensions from lymphoma tissue were expanded with anti-NKp46/anti-CD2-coated beads in the presence of IL-2." (PMID 31126350, 2019). "All of the cell lines have been derived from patients with leukemia/lymphoma and are dependent on IL-2 for the proliferation and effector functions." (PMID 31163679, 2019). "Despite the removal of the E.G7 cells, T cell production of IL-2 was nearly the same as when E.G7 lymphoma remained in the culture during T cell activation." (PMID 31602007, 2019). "There has been little work in this area but one prospective study showed that IFNγ levels (together with levels of IL-2 and ICAM) associate with the risk of developing lymphoma." (PMID 29293620, 2018). "On the other hand, patients with lymphoma exhibited a loss of functional EBV-specific CD4+ T cells, as demonstrated by TNF-α+ (p = 0.008); IFN-γ+ (p = 0.025); and IL-2+ (p = 0.009) counts." (PMID 30337929, 2018). "We next examined if IL-2 production by lymphoma cells resulted in activation of WASp KO NK cells in vivo." (PMID 27477778, 2016). "We identify that IL-2, either exogenously provided or produced naturally by lymphoma cells, restored killing capacity by WASp KO NK cells in vivo." (PMID 27477778, 2016). "Despite its broad spectrum of binding activity, the cytotoxic activity of mAb 4713 was limited to IL-2-independent lymphoma cell lines." (PMID 27028595, 2016). "To determine the response of WASp KO NK cells to lymphoma cells with high production of IL-2, we injected A20 lymphoma cells labeled with the DiR fluorescent dye into wildtype and WASp KO Balb/c mice and monitored tumor growth by IVIS during 6 days." (PMID 27477778, 2016). "Based on our findings, IL-2 appears to be a crucial tumor marker to detect lymphoma, but the test also showed a high rate of false positive findings." (PMID 26115010, 2015).
lymphoma (continued). "An active biological role of sIL-2R has been described in lymphoma wherein sIL-2R binds IL-2 and the sIL-2R-IL-2 complex promotes environmental T cell differentiation into regulatory T-cells." (PMID 26375984, 2015). "Ex vivo IL-2-activated NK-cell infusions were compared with supplemental intravenous IL-2 boluses on days 28 and 35 during daily subcutaneous IL-2 administration in patients with relapsed lymphoma or metastatic breast cancer." (PMID 26029215, 2015). "In summary, our present work demonstrated a novel pathway related to lysosomal ceramide, CTSB, and XIAP in IL-2(−)-induced NK/T lymphoma cell apoptosis." (PMID 25855965, 2015). "Naturally, evaluating the levels of IEP and IL-2 was the most efficient way to identify the multiple myelomas and lymphomas." (PMID 26115010, 2015). "The ASM–ceramide–CTSB signaling axis is a novel pathway of ceramide-mediated apoptosis in IL-2-deprived NK/T lymphoma cells." (PMID 25855965, 2015). "Regarding IL-2, this tumor marker identified 9 (39.1%) of 23 lymphomas and detected ten SMUP patients who did not have lymphomas as false positives." (PMID 26115010, 2015). "KHYG-1 NK/T lymphoma cells require IL-2 for their proliferation and survival and undergo apoptosis by IL-2(−) even in the presence of serum." (PMID 25855965, 2015). "The combination of lunasin and cytokines (IL-12 plus IL-2) was capable of restoring IFNγ production by NK cells from post-transplant lymphoma patients." (PMID 24363024, 2014). "Supernatants from media of the IL-2 producing lymphoma cells were concentrated and then similarly separated." (PMID 25019288, 2014). "MALDI-TOF/TOF analysis of the 30 kD band produced by EL-4 T lymphoma cells and recognized by an anti-IL-2 antibody." (PMID 25019288, 2014). "Serum soluble interleukin-2 (IL-2) receptor (sIL-2R) was discovered in supernatants of adult T-cell leukemia/lymphoma (ATLL) cell lines, and now has been recognized as a tumor-related biomarker of malignant lymphomas, including B-cell malignancies." (PMID 24236041, 2013). "Targeted IL2 promotes the recruitment of NK cells and macrophages into lymphoma lesions sustaining the anti-lymphoma activity of the anti-CD20 antibody." (PMID 23028547, 2012). "In these lymphoma patients, IL-2 treatment results in increased absolute numbers of NK cells, with no significant change in T-cell subsets or plasma HIV RNA levels." (PMID 22319542, 2012). "Together with the CD20 targeting antibody rituximab, the antibody-targeted IL2 improved infiltration and activation of immune effector cells in lymphoma lesions resulting in the eradication of those lesions that were not cured with rituximab alone." (PMID 23028547, 2012). "Jurkat cells, a human T-cell leukemia/lymphoma cell line known to produce IL-2, were used as a positive control." (PMID 23675235, 2011). "Subsequently, to identify the potential source of IL-2 for lymphoma cells in vivo, we performed gene expression and immunochemical analyses." (PMID 23675235, 2011). "Our study shows that the downregulation of miR-26a is another global pathway for the increased IL-2 expression in the lymphoma cell lines transformed by the avian oncogenic viruses MDV, ALV and REV." (PMID 20441582, 2010). "The binding of these cytokines to high affinity receptors on target cells, e.g. L929fibroblasts and IL-2 in HuT78 T lymphoma cells, were also suppressed by the agents." (PMID 18475825, 1998). "We therefore conclude that the decrease in CD16 expression on γδ T cells mediated by stimulation with zoledronate and IL-2 is not a disadvantage but can be even associated with increased anti-lymphoma activity of stimulated γδ T cells." (PMID 41369406, 2025). "NK92 is an IL-2-dependent immortalized cell line derived from a patient with lymphoma." (PMID 38195534, 2024). "Hence, we further compared the use of 161519 TriKE and 1619 BiKE under the influence of IL-2 regimens using a xenograft murine model loaded with Namalwa lymphoma cells." (PMID 33299651, 2020).